MET (MET proto-oncogene, receptor tyrosine kinase)
Diseases named in the same sentence as MET in open-access papers (continued):
Sharing a sentence is not in itself a finding about the gene and the disease.
tumor (continued). "The use of matched therapy was relatively low in patients with tumor alterations such as ERBB2 mutation (14/43, 32.6%), MET amplification (32/99, 32.3%), KRAS G12C (8/135, 5.9%), and EGFR exon 20 insertion (1/25, 4.0%)." (PMID 35877242, 2022). "Other targeted therapies have been investigated in clinical trials in patients with advanced gastric cancer, including Cetuximab and Panitumumab in EGFR-positive tumor, or Rilotumumab and Onartuzumab in MET-positive tumor." (PMID 36230592, 2022). "MET proto-oncogene receptor tyrosine kinase plays a pivotal role in multiple cellular processes such as carcinogenesis and tumor progression in several solid tumor types." (PMID 36483096, 2022). "The chitosan nanoparticle-mediated delivery of miRNA-34a inducts autophagy and apoptosis by downregulation of MET and Axl and c-Myc, which then lead to the inhibition of tumor growth and metastasis preservation of bone integrity in vivo." (PMID 35457012, 2022). "It acts as a transcription factor regulating genes involved in EMT, such as c-MET (which can directly induce metastasis), impacts tumour cell migration and invasion, and induces metastasis in solid cancers." (PMID 35884519, 2022). "The expression of EGFR/MET was up-regulated in circulating tumor microemboli (CTM) to accelerate IL-8 production and resistance to the lethal effect of leukocytes." (PMID 35428350, 2022). "HGF was shown to be produced by stromal cells in co-culture with HB cells, suggesting a paracrine mechanism of HGF stimulation, while analysis of tumor sections revealed high expression of c-MET by epithelial tumor cells." (PMID 36034555, 2022). "An over-activation of c-MET pathway plays a key role in carcinogenesis, tumor progression and resistance to antineoplastic treatments in various human cancer types." (PMID 36498560, 2022). "For example, exosomal circ-PDE8A has been showed association with tumor progression and lymphatic invasion in pancreatic ductal adenocarcinoma (PDAC) via the miR338/MACC1/MET pathway." (PMID 35505392, 2022). "Altogether, our in vitro drug testing results demonstrate that combined PD-1/MET antagonism enhances direct tumor cytotoxicity compared to monotherapy regimens." (PMID 35804822, 2022). "The orthotopic liver xenograft tumor model demonstrated that HGF/MET signaling plays a significant role in CD44v6+ HCC cells." (PMID 36387747, 2022). "The pivotal genes CDK6 and MET of the T. hemsleyanum-inhibited tumor were confirmed, providing a new theoretical basis for the clinical application of T. hemsleyanum." (PMID 35480115, 2022). "Dysregulation of hepatocyte growth factor/mesenchymal-epithelial transition factor gene (HGF/c-MET) pathway plays a crucial role in human carcinogenesis, tumor progression and resistance to antineoplastic treatments." (PMID 36498560, 2022). "In the xenograft model, the tumor volume, frequency of T790M, and mRNA expression level of MET were measured." (PMID 35326664, 2022). "In vitro and in vivo studies have shown that tepotinib inhibited the growth of MET-dysregulated tumor cells, and mice implanted with tumor cells expressing oncogenic active MET had a reduced formation of metastases." (PMID 35565287, 2022). "Our data suggest that EMI-137 circulates through the lymphatic system and eventually binds specifically with MET-expressing PTC tumor cells." (PMID 35389070, 2022). "Abnormal activation of c-MET leads to the progression of tumor growth and metastatic cancer cells, which makes it an important for drug target for cancer treatments." (PMID 35778602, 2022). "Aberrant activation of MET pathway contributes to tumor progression by promoting tumor cell proliferation and EMT." (PMID 35301291, 2022). "The induction of MET has clinical potential as it can block the initial EMT stages that favor tumor cell dissemination, while its inhibition can curb metastatic outgrowth at distant sites." (PMID 35565186, 2022).
tumor (continued). "This instructed CAFs to over-secrete HGF, that activated the MET pathway in tumor cells, thus favoring their escape from MET or EGFR targeting." (PMID 36324182, 2022). "So, we investigated the co-inhibition of NOTCH and MET pathways in our tumor cell context to evaluate potential synergies on malignant cell features." (PMID 35574376, 2022). "In the C57 xenograft model, CTM with high EGFR/MET expression was detected in the blood vessels of lung metastasis mice, which was higher than that in tumor tissues, indicating EGFR/MET as a suitable marker for CTC/CTM detection." (PMID 35428350, 2022). "Mutations in oncogenic factors including EGFR, ALK, BRAF, or MET, which can change the immunological tumor micro-environment, can enhance tolerance to PD1/PD-L1." (PMID 36499382, 2022). "Newly acquired MET D1228H mutations and EGFR amplificated were detected in patient-resistant tumor specimens." (PMID 36338758, 2022). "In this study, MET gene copy number (GCN) was assessed in tumor tissue by next generation sequencing." (PMID 35129063, 2022). "METex14 leads to the loss of ubiquitin ligase binding sites, a reduction in receptor ubiquitination, and persistent MET activation, resulting in tumor cell survival and acquired resistance." (PMID 35840984, 2022). "The possibility exists that MET is highly activated in low expressing tumors, e.g., if there are tumor areas with high levels of HGF in the TME." (PMID 35326642, 2022). "Inhibition of c-MET in hematopoietic cells was previously shown to decrease total NO levels at the tumour site, a process correlating with decreased iNOS by neutrophils." (PMID 35041723, 2022). "Proliferative tumours were characterized by high expression of the c-MET, ARID1A, CTNNB1, RAF1, LGR5, and GLUL1 genes." (PMID 36345011, 2022). "This novel signaling pathway of decorin/MET/mitostatin/Parkin transduces signals from high affinity decorin/MET interactions via an unidentified kinase or similar effector, for sustained tumor cell mitophagy." (PMID 35159071, 2022). "In order to evaluate the potential synergistic antagonism of PD-1 and MET in a more clinically relevant model with a tumor microenvironment mirroring the original tumor, we next performed drug testing in PD-1+/MET+ PDAC PDOs hPT1 and hPT4." (PMID 35804822, 2022). "We queried the association between the mRNA expression levels of DPP4/CTNNB1/MET and tumor infiltrations of immunosuppressive cells using the TCGA cohorts." (PMID 35205190, 2022). "In the SU2C cohort, 516 gene sets were exclusively enriched in the high‐SNAI2 group; these gene sets play important roles in tumor invasion and metastasis, such as focal adhesion, hedgehog, MET, PDGFP, and integrin signaling." (PMID 34792282, 2022). "Cabozantinib is a small-molecule tyrosine kinase inhibitor of MET and VEGFR 1-3, RET, KIT, AXL, and FLT3, all of which are associated with tumor pathogenesis." (PMID 35000616, 2022). "Foretinib was identified in our screen using patient MA01 tumor organoids and is an MET/VEGFR inhibitor." (PMID 35743016, 2022). "An in vivo study has shown that oncogenic MET/PIK3CA synergistically induces tumor aggressiveness and chemoresistance." (PMID 35621626, 2022). "The c-MET/HGF signaling is also known to contribute widely in metabolic reprogramming of tumor cells." (PMID 35081970, 2022). "Despite having potent activity against MET, studies found no anti-tumour effect in tumours with MET mutations, though, subsequently demonstrated efficacy against tumours with MET exon 14 skipping alterations." (PMID 35941175, 2022). "HGF/c-MET also interacts with the Src/STAT3/FAK/ERK signaling pathway to induce resistance to platinum-based drugs in tumor cells." (PMID 35684449, 2022). "The authors demonstrated in a murine model that the inhibition of the HGF/c-MET axis impaired the recruitment of immunosuppressive neutrophils into tumors, thus allowing T cell tumor infiltration and enhancing the effect of immunotherapy." (PMID 36010840, 2022).
tumor (continued). "Previously, we have reported that aberrant activation of the MET receptor modulates the cellular response to IR by rewiring key DNA damage response (DDR)-related phosphorylations in some tumor cell lines featuring MET activation." (PMID 36494469, 2022). "Other studies reported a reduction in the expression of miR-27b in OSCC specimens, assuming this miRNA’s role as a tumor suppressor through targeting the MET oncogene in this disease." (PMID 36612284, 2022). "Several different approaches were used to test for MET dysregulation, including overexpression as IHC2+ or IHC3+ in ≥50% of the tumor cells by IHC and MET GCN ≥ 5 or MET/CEP7 ratio ≥ 2.0 by FISH." (PMID 35565287, 2022). "HGF is a pleiotropic growth factor and cytokine, whose upregulation promotes tumor cell survival, motility, and proliferation, and its receptor, HGFR (a.k.a. c-MET), is a well-known oncogene." (PMID 35366939, 2022). "Immunohistochemistry also further demonstrated a high expression of c-MET in tumor tissues of the PSC and HGF groups." (PMID 35693705, 2022). "Aberrant activation of EGFR and MET signaling pathways drives tumor cell growth and proliferation in lung cancer." (PMID 36341333, 2022). "In HCC, HGF is expressed by stromal cells or tumor cells and binds to its specific receptor, c-MET, to play a part in tumor onset, proliferation, invasion and metastasis." (PMID 36109787, 2022). "The axis MET/Wnt/β-catenin is critical to maintaining cancer stem cells, which possess high levels of MET and Wnt/β-catenin to drive tumor propagation." (PMID 36430388, 2022). "In particular, the greatest tumor-reduction effect was observed in the MET amplification subgroup treated with savolitinib, a MET inhibitor, compared to the other subgroups." (PMID 35751736, 2022). "For the phase Ib part, the patient selection criteria were either MET GCN ≥ 5 and/or a MET/CEP7 ratio ≥ 2.0 or MET overexpression as IHC2+ or IHC3+ in ≥ 50% of the tumor cells." (PMID 35565287, 2022). "The authors suggested that in this model of GBM, anti-c-MET therapy had an indirect anti-angiogenic effect, potentially by decreasing proteolysis within the tumor extracellular matrix, thereby inhibiting neovascular spread." (PMID 36034555, 2022). "Aberrant activation of c-MET signalling has been shown to participate in tumour progression, prompting the development of c-MET inhibitors." (PMID 35041723, 2022). "MET, also called mesenchymal-epithelial transformation factor, was firstly validated in tumor progression." (PMID 36147332, 2022). "SHR-A1403 has shown significant anti-tumour activity in a variety of tumour cell lines with high c-MET levels, xenograft mouse models, and patient-derived xenografts (PDX) models of HCC." (PMID 33816276, 2021). "According to the Reactome analysis, biological processes of the genes in the ceRNA network from tumor tissue were mainly related to MET pathways." (PMID 34630508, 2021). "Some of these ADC targets are known oncoproteins, such as EGFR (targeted by two ADCs), HER-2, c-MET, Trop-2 or tumor antigens, such as tissue factor (CD142) and B7-H3, the latter being recently validated as a novel immune-checkpoint." (PMID 34206707, 2021). "Cabozantinib, a combinatorial VEGFR and c-MET inhibitor, exerted a greater anti-tumor effect than c-MET inhibition alone, suggesting a potential mechanism independent of c-MET inhibition." (PMID 34830850, 2021). "High levels of VEGF receptor (VEGFR), VEGF, c-MET, and the c-MET ligand hepatocyte growth factor (HGF) are associated with poor prognosis and tumor aggressiveness." (PMID 34180036, 2021). "The in vitro cabozantinib screen was aligned with MET and RET expression and only showed efficacy in MET and RET positive LuCaP 93 cells, demonstrating that cabozantinib can elicit direct effects on SCNPC tumor cells driven by MET or RET activity." (PMID 33471819, 2021).
tumor (continued). "Activation of c-MET transcription has been reported in response to hypoxic tumor conditions in cultured cell lines derived from tumor samples." (PMID 34180036, 2021). "As the c-MET expression is lower in corresponding normal tissues, such tumours are an ideal target for antibody-based biological therapy." (PMID 33816276, 2021). "For example, YYB-101, a humanized neutralizing antibody specifically binding to HGF, inhibits c-MET activation and cell scattering in vitro and suppresses tumor growth in HCT116 xenograft mouse models." (PMID 33466394, 2021). "c-MET is considered a driver of cancer progression, impacting tumor growth and tumor-supporting stroma." (PMID 33731699, 2021). "We analyzed TCGA HCC tissue sample gene expression data by grouping the tumor tissue samples into quartiles according to their normalized MET mRNA expression levels." (PMID 34059694, 2021). "It is commonly expressed in GB and strong MET expression was found in tumor cells, blood vessels and peri-necrotic areas of glioma samples." (PMID 34209513, 2021). "All studies showed consistent MET overexpression in tumors compared with non-tumor surrounding tissue (fold-change=5.96 in GSE20347; fold-change=3.83 in GSE45670; fold-change=6.02 in GSE75241)." (PMID 34037097, 2021). "For example, ATM is highly expressed in the microvascular proliferative zones of the tumor, EGFR is highly expressed in the cellular bulk of the tumor while MET is enriched in the leading edges and the necrotic tumor regions." (PMID 33765907, 2021). "The successful implantation required exogenous activation of MET in the tumor cells by continued administration of a humanized antibody agonist of the receptor." (PMID 34680266, 2021). "A number of preclinical studies have demonstrated that MET inhibition is able to reverse chemotherapy resistance in various different tumour types." (PMID 33526881, 2021). "These methylation statuses of c-MET and EGFR in CRC were also consistently associated with the tumor stage, dysfunctional T cell phenotypes, and shorter OS of CRC patients." (PMID 34512327, 2021). "Intratumor heterogeneity was evaluated in at least four tumor biopsies from five patients and two cases showed a consistent increase in MET expression (at least two-fold) in all tumor samples." (PMID 34037097, 2021). "Several studies have also reported that a combined VEGFR/c-MET inhibition reduced the angiogenic response in primary tumors and effectively decreased tumor progression." (PMID 33731699, 2021). "A total of 42 somatic hot spot mutations were detected in tumor tissue DNA, and 39 mutations were detected in CTC-DNA, all of which included common changes in PTEN, MET, EGFR, RET, and FGFR3." (PMID 34178679, 2021). "The MR007 PDX model was developed from an osimertinib-resistant EGFR-mutant patient whose drug refractory tumor harbored MET amplification and was found to be sensitive to single-agent savolitinib in vivo." (PMID 34516823, 2021). "The role played by TNC in MET-mediated tumor-stroma cross-talk has been further investigated by knocking-down TNC expression." (PMID 34298732, 2021). "It provided a robust TGI (tumor growth inhibition) in the MET-amplified GTL-16 model and a U87MG model exhibiting the HGF/c-MET autocrine loop." (PMID 35087755, 2021). "Overall, 40% of treated patients had MET-driven tumor, as defined by chromosome 7 copy gain, focal MET or HGF gene amplification, or MET kinase domain mutations." (PMID 34359706, 2021). "In HNSCC, miR-34a acts as a tumor suppressor and physically interacts with and functionally targets the proto-oncogene MET." (PMID 33596979, 2021). "Using the U87MG GB model, [89Zr]Zr-onartuzumab achieved higher tumor accumulation (i.e., tumor/muscle ratios) and effectively visualized changes in MET expression." (PMID 34209513, 2021).
tumor (continued). "Within the present study we showed that c-MET plays a role for cellular plasticity and stemness in HNSCC, which are major determinants of tumor radioresistance, and provide support for the potential of c-MET targeting strategies for HNSCC radiosensitization." (PMID 33919702, 2021). "In GBM, when HGF binds to MET and induces receptor dimerization and auto-phosphorylation, it triggers a cascade within the nucleus that signals for tumor growth, invasion, and metastasis." (PMID 34055785, 2021). "Researchers have found that the HGF/MET signaling pathway is abnormally activated in many malignant tumors and that this abnormal activation promotes tumor proliferation, survival and metastasis." (PMID 34568049, 2021). "There is a report about VEGFR-2 and the hepatocyte growth factor receptor (MET) having a synthetic effect on tumor growth." (PMID 33679971, 2021). "This study presents strong evidence that miR-34a-5p acts as a tumor suppressor and physically interacts with and functionally targets the proto-oncogene MET." (PMID 33596979, 2021). "Activating c-MET pathways in tumor cells during tumor progression enhances the ability to disaggregate from surrounding tumor cells, which further destroys the basement membrane and improves cell mobility and metastatic risk." (PMID 34261467, 2021). "OMO-1 reduced non-c-MET addicted 4T1 tumor progression dose dependently as monotherapeutic and provided additional disease reduction in combination with cisplatin." (PMID 33731699, 2021). "Accordingly, it can be inferred that histone methyltransferases and demethylases that preferentially target H3K36me2 are potential targets for pharmacologically inhibition of MET at the end stage of tumor metastasis." (PMID 33996581, 2021). "Taken together, these findings indicate that MET inhibition and PD-L1/PD-1 pathway blockage cooperatively inhibited tumor growth." (PMID 34479614, 2021). "In this study, based on a cohort of 155 consecutive MM patients, we used a well-established method of IHC to identify cases having moderately (2+) or strongly (3+) increased MET protein expression in the tumor tissue." (PMID 34884673, 2021). "In a number of human tumours, overexpression of MET leads to the acquisition of a stem cell-like phenotype." (PMID 33526881, 2021). "One of the limitations of our study derives from the fact that MET is known to be expressed not only in tumor cells but also in normal epithelial, dendritic, and other immune cells." (PMID 33236532, 2021). "Small hairpin RNA-mediated c-MET knockdown dramatically suppressed tumor growth in a SW480 xenograft mouse model as well as SW480 cell proliferation in vitro." (PMID 33466394, 2021). "In CRC, c-MET overexpression is usually correlated with tumor progression, metastasis, and poor prognosis: Seemingly, accounted for by enhanced c-MET transcription driven by aberrant WNT signaling." (PMID 33562604, 2021). "Unlike the current clinically available c-MET inhibitors and c-MET mAbs, which exert anti-tumour activity by inhibiting c-MET signal transduction, the new c-MET ADC SHR-A1403 exerts anti-tumour activity through the intracellular release of SHR152852." (PMID 33816276, 2021). "This does not negate the possible direct effect of cabozantinib on MET and RET activity in the tumor cells of the MET+/RET+ LuCaP 93 xenografts." (PMID 33471819, 2021). "Accordingly, targeting the MET/STAT3 signaling pathway potentiates the anti-tumor efficacy of PI3K/AKT inhibitors in NSCLC tumor-bearing mice." (PMID 34944848, 2021). "HGF/MET has been demonstrated to play an essential role in the ability of a tumour to metastasize by regulating cell motility, migration, proliferation and angiogenesis, and in addition, modulating the tight junction (TJs) cell to cell barrier." (PMID 33917539, 2021). "PTPRZ1-MET exerts its oncogenetic capacity by hijacking the MET pathway resulting in tumor formation and if left unchecked, metastasis." (PMID 34671307, 2021).